NOD2 (nucleotide binding oligomerization domain containing 2)
Diseases named in the same sentence as NOD2 in open-access papers (continued):
Sharing a sentence is not in itself a finding about the gene and the disease.
bacterial infection (continued). "We also observed induced protein and mRNA production such as NOD1, IL-10, MCP-1, NOD2, and RIP2 in RAW 264.7 cells under MOMP stimulation compared to normal cells, which are thought to be involved in various immune responses against bacterial infection." (PMID 34812410, 2021). "Primary corneal fibroblast cells expressed NOD1 and NOD2, elevated NLRC4 after bacterial infection, but reduced NLRP1, NLRP3, NOD1, and NOD2 mRNA levels following LPS stimulation." (PMID 32019187, 2020). "It plays an important function in recognizing intracellular bacterial infection through regulating and transducing NOD1 and NOD2 signaling." (PMID 29874851, 2018). "In response to bacterial infection, CARD15/NOD2 acts as an intracellular bacterial receptor and activates the kappa B nuclear factor (NF-κB), particularly after recognizing the bacterial wall component muramyl dipeptide (MDP)." (PMID 30648106, 2018). "In addition, our results might help to explain (i) how innate immune-tolerant humans are highly susceptible to secondary bacterial infections and (ii) the mechanism by which NOD2 signalling is negatively regulated to maintain immune homeostasis and tolerance." (PMID 28656966, 2017). "Due to the ability of NOD2 to sense bacterial MDP, its role during bacterial infections and the induction of inflammatory responses has been widely studied." (PMID 28004792, 2016). "Immunosuppressant therapy may downregulate NOD2 expression in CD8+ T lymphocytes, monocytes, and DCs in SLE patients which subsequently IL-10 reduction, contributing towards the regulation of immunopathological mechanisms of SLE, at the expense of increasing risk of bacterial infection." (PMID 21886831, 2011). "This leads us to speculate that the Nod2 Nacht domain mutations may mimic in part an association of the protein with bacteria resulting in an elevated basal cellular anti-bacterial signaling response (in the absence of a bacterial infection)." (PMID 20531959, 2010). "Since ELMO1 and NOD2 regulate intestinal immune response against bacterial infections, we assessed if ELMO1 and NOD2 could interact physiologically." (PMID 36694274, 2023). "In CD-associated NOD2 shift-mutant pure cells, mutant NOD2 fails to recruit ATG16L1 to the plasma membrane, thereby limiting the autophagic response triggered by intracellular bacterial infection." (PMID 37168865, 2023). "Nucleotide-binding oligomerization domain 2 (Nod2) interacts with CARD9 to promote the recognition of MDP and the activation of the JNK and p38 signaling pathways and ultimately regulates the production of inflammatory cytokines against bacterial infection." (PMID 36439825, 2022). "Although these NLRs share common signaling mediators to respond to bacterial infection and HFD consumption, the disparate roles of NOD1 and NOD2 in HFD mouse models suggest the use of novel and distinct signaling pathways by NOD1 and NOD2 downstream of RIP2 in the context of metabolic stress." (PMID 33503814, 2021). "For example, the NLR Nod2 plays an essential role in the activation of NF-κB and MAPK signaling pathways and robust production of proinflammatory cytokines and chemokines in neutrophils in response to bacterial infection." (PMID 33921651, 2021). "Moreover, intracellular proteins NOD2 and NOD1 exert critical effects on autophagy induction upon bacterial invasion by recruiting ATG16L1 proteins to the site of bacterial infection on cell membrane." (PMID 32940422, 2020). "NOD2 is an intracellular binding partner of EMMPRIN and is important during bacterial infections." (PMID 29419744, 2018). "Although we found upregulated mRNA expression, we did not detect enhanced protein levels of NOD1 and NOD2 in BLP-tolerised BMMs after bacterial infection." (PMID 28079153, 2017).
bacterial infection (continued). "Our data emphasize the protective nature of NLRP10 against microbial pathogens, thus adding NLRP10 to the group of NLR family members such as NOD1, NOD2, NLRC4, NLRP3, and NLRP12 that initiate pro-inflammatory signaling to mediate host resistance toward bacterial infections." (PMID 29163529, 2017). "In addition to this cytokine response initiated by bacterial infection, it has also been shown that upon exposure to MDP, NOD2 plays a key role in the initiation of the autophagy pathway." (PMID 23119165, 2012). "Moreover, both NOD1 and NOD2 can activate autophagy during bacterial infection by a mechanism which is independent of RIP2 and NF-κB, by recruiting the autophagy protein ATG16L1 to the plasma membrane at the bacterial entry site." (PMID 30791886, 2019). "However, knockdown of both NOD1 and NOD2 impaired bacteria-induced activation of the NF-κB pathway in BLP-tolerised BMMs, as evidenced by significantly reduced nuclear translocation of p65 in response to bacterial infection." (PMID 28079153, 2017). "Some of these feedback systems must involve the negative regulation of NOD1, NOD2 and RIG1, since these receptors are known to be activated by the viral and bacterial infections discussed here, yet they do not appear to be activated during cytokine release syndromes." (PMID 33672738, 2021).
cancer (75 papers, 2010 to 2026). A tumor composed of atypical neoplastic, often pleomorphic cells that invade other tissues. "In CRC, however, the association between NOD2 polymorphisms and the risk of developing cancer remains controversial." (PMID 40563649, 2025). "If activation of NOD2 negatively regulates TLR-mediated chronic inflammation, it is likely that NOD2 attenuates inflammation-associated cancer driven by TLRs." (PMID 36268029, 2022). "Since Z-100 activates NOD2, it is more likely to suppress cancers for which NOD2 polymorphisms are a cancer risk." (PMID 35785036, 2022). "We found that NOD2 was a cancer-promoting gene, as it was enriched in the high-risk group and associated with poor prognosis among LIHC patients." (PMID 35659304, 2022). "Both NOD1 and NOD2, altering the balance of anti- and pro-inflammatory cytokines, can modulate the risk of cancer development." (PMID 33324568, 2020). "A number of NOD1 and NOD2 SNPs have been associated with a higher risk of cancer development in many malignancies." (PMID 30837326, 2019). "By altering the balance between pro- and anti-inflammatory cytokines, NOD1 and NOD2 modulate the risk of cancer." (PMID 28771183, 2017). "For NOD2 rs2066845 C/G (G908R) polymorphism, CG genotype carriers were observed to be significantly associated with increased risk of cancer compared with GG carriers (OR = 1.39, 95% CI = 1.03–1.87, P = 0.030)." (PMID 24586700, 2014). "The three polymorphisms (rs2066844, rs2066845 and rs2066847) which were observed to be associated with increased risk of cancer in this meta-analysis were all located at the leucine-rich region (LRR) of NOD2 protein." (PMID 24586700, 2014). "Results from previous individual studies investigating the associations between NOD2 polymorphisms and cancer risk were inconclusive." (PMID 24586700, 2014). "The present meta-analysis unraveled that NOD2 polymorphisms were observed of different associations with cancer in various cancer subgroups." (PMID 24586700, 2014). "Polymorphisms of the NLR genes NOD1 (NLRC1) and NOD2 (NLRC2) have been correlated with altered cancer risk." (PMID 24681825, 2014). "With respect to NOD2 rs2066844, rs2066845 and rs2066847 polymorphisms, the dominant effect models of the three polymorphisms all indicated significantly increased cancer risk (OR for rs2066844 = 1.32; OR for rs2066845 = 1.32; OR for rs2066847 = 1.23)." (PMID 24586700, 2014). "More recently, NOD2 gene polymorphisms have been associated with higher predisposition to a number of cancer types, including increased risk of gastric cancer in H. pylori-infected patients." (PMID 25594025, 2014). "Many studies consider NOD2 as a potential risk factor that promotes the occurrence of cancer." (PMID 40468178, 2025). "Nevertheless, there is a possibility that the polymorphism has a minor effect or may co-occur with other polymorphisms to alter NOD2 protein function, explaining why a significant association was observed in several cancers." (PMID 40563649, 2025). "Many studies consider NOD2 to be one of the potential risk factors that promote cancer occurrence." (PMID 40468178, 2025). "A meta-analysis investigating overall cancer risk in relation to NOD2 polymorphisms showed that the NOD2 rs2066844 C/T, rs2066845 C/G, and rs2066847 (3020insC) polymorphisms might be associated with increased cancer risk." (PMID 38755492, 2024). "Furthermore, the anti-inflammatory function of NOD2 is dependent on the recognition and binding of bacteria and their derivatives, and when this association is inadequate, NOD2 contributes to chronic inflammation and promotes cancer." (PMID 37324457, 2023). "The NOD2 c.3020insC allele has been shown to occur in 7.3% of the Polish population and could therefore be considered a common genetic risk factor for cancer." (PMID 35478773, 2022). "Sixteen cancer patients who carried the NOD2 variant had died by February 2021." (PMID 35478773, 2022).
cancer (continued). "Inflammation is a risk factor for some cancers, and polymorphisms in Nod2 are associated with increased risk for colorectal cancer and may be associated with increased risk for lymphoma, gastric, breast, ovarian, lung, and laryngeal cancers." (PMID 33239685, 2020). "Furthermore, NOD2 deficient mice are seemingly more prone to colitis and colitis-related cancer due to induced instability in the composition of gut microbiome." (PMID 30837326, 2019). "NOD2 rs2066844 C/T, rs2066845 C/G and rs2066847 (3020insC) polymorphisms might be associated with increased cancer risk." (PMID 24586700, 2014). "The aim of this meta-analysis was to elucidate whether NOD2 polymorphisms were associated with cancer risk." (PMID 24586700, 2014). "Meta-analysis results of the association between NOD2 polymorphisms and cancer risks." (PMID 24586700, 2014). "Emerging evidence indicated that common polymorphisms of NOD2 might impact individual susceptibility to cancer." (PMID 24586700, 2014). "As Salmonella ΔmsbB is under investigation as an anti-cancer vaccine strain, our results indicate that this strain may cause inflammatory complications at least in persons with mutations in Nod1 or Nod2 pathways." (PMID 25423082, 2014). "In addition, T allele of NOD2 rs2066844 C/T polymorphism was associated with significantly increased risk of cancer compared with C allele." (PMID 24586700, 2014). "NOD2 deficiency in TME could not only induce inflammatory diseases but also resulted in cancers." (PMID 34268854, 2021). "Several of these diseases have links to inflammation and/or cancer, thus highlighting the importance of the NOD2/RIPK2 pathway." (PMID 40095546, 2025). "NOD1 and NOD2 are widely expressed in immune cells and serve as crucial PRRs, demonstrating dual roles in cancer regulation." (PMID 39329913, 2024). "Following MDP treatment, we found RFP+ cells around cancer colonies in Nr4a1–/– Nod2–/– mice that received either Ccr2RFP/RFP or Ccr2RFP/+ bone marrow." (PMID 39545417, 2024). "NOD2 controls intestinal inflammation thereby decreasing the incidence of inflammatory driven cancers, including CRC, by downregulation of TLR pathways." (PMID 38742117, 2024). "However, the role of Nod2 deficiency in cancer metastasis remains unknown." (PMID 39545417, 2024). "In the cervical tissues of patients with metastatic cervical squamous cell carcinoma (CSCC), NOD1 and NOD2 exhibit pronounced upregulation, thereby facilitating cancer cell proliferation and metastasis." (PMID 39329913, 2024). "Given that NOD2 agonists have been approved for human use, our findings have potential clinical implications for patients with cancers resistant to current immunotherapies." (PMID 39545417, 2024). "In recent years, emerging evidence has highlighted the crucial roles played by NOD1 and NOD2 in regulating infectious diseases, metabolic disorders, cancer, and autoimmune conditions, among others." (PMID 39329913, 2024). "To effectively predict survival, we screened two inflammation-related genes (RIPK2 and NOD2) that were highly expressed in cancer tissues and which influenced clinical outcomes." (PMID 38742117, 2024). "Along with this, the benefits of NOD2 agonists seem to outweigh such potential unwanted effects when used against other types of cancer." (PMID 38919608, 2024). "NOD1 and NOD2 represent promising targets for cancer therapy, warranting a comprehensive understanding of their alterations across distinct stages and phenotypes, which holds paramount significance." (PMID 39329913, 2024). "The Gene Expression Profiling Interactive Analysis (GEPIA) (cancer-pku.cn) database showed that NOD2 expression was downregulated in the ESCA cell lines compared with the esophageal epithelium cell lines." (PMID 36316517, 2023). "All these pieces of evidence shift the belief that the involvement of NOD2 in cancer is via dysbiosis as this increased cancer propensity was seen to be transferable too in co‐housing." (PMID 37706437, 2023).
cancer (continued). "NOD2 activation has been shown to suppress anti-cancer immunity induced by the gut colonization with Enterococcus hirae and Barnesiella intestinihominis." (PMID 36268029, 2022). "Further elucidation of the molecular mechanisms by which NOD1 and NOD2 activation regulate the development of liver injury and cancer is required for the application of NOD1 and NOD2 ligands as treatments of human diseases." (PMID 36268029, 2022). "GO and KEGG enrichment analyses further showed that the genes and proteins correlated with the upregulation of NOD1 or NOD2 were involved in cell proliferation, cytokines, and pathways in cancer such as ERK, NF-κB, and IL-8." (PMID 35130902, 2022). "After 24 h and 48 h co‐culture, lower NOD2 expressions were found in THP‐1 co‐cultured with cancer cells." (PMID 34268854, 2021). "The role of NOD2 in cancer immunity is controversially reported, and it varies depending on the types of cancer." (PMID 32144252, 2020). "In this study, we identified nucleotide binding oligomerization domain 2 (NOD2), an innate immune sensor, as an efficient direct regulator of AMPK pathway; and loss of its expression in cancer cells promoted HCC progression and resistance to chemotherapy." (PMID 32144252, 2020). "The cytosolic nucleotide‐binding oligomerization domains 1 and 2 receptors (NOD1 and NOD2) are important components of the innate immune system and constitute interesting targets in terms of strengthening the immune response against cancer cells." (PMID 30548868, 2019). "To conclude, the innate immune receptors NOD1 and NOD2 constitute promising targets in cancer immunotherapy." (PMID 30548868, 2019). "Both NOD1 and NOD2 are thought to engage not only in innate and adaptive immune responses, but also in the interaction between autophagy and cancer." (PMID 28771183, 2017). "With the development of whole genome sequencing, plenty of data about NOD2 gene in cancers can be acquired online, such as TCGA, Gene Expression Omnibus (GEO) and so on." (PMID 29254180, 2017). "NOD1 and NOD2 have both been defined as seminal players in gut homeostasis, providing protection against colitis and cancer." (PMID 25594025, 2014). "The amino acid substitutions caused by these polymorphisms would alter protein function or splicing, thus influencing the role of NOD2 in the regulation of apoptosis and chronic inflammation and finally leading to cancer." (PMID 24586700, 2014). "Our data from ex vivo cultured ileal biopsies of otherwise healthy individuals undergoing endoscopy for cancer surveillance suggested that TNFα-induced NOD2 expression was also reduced by CSE." (PMID 21931826, 2011). "NOD2, a cytoplasmic pattern recognition receptor primarily known for bacterial pathogen recognition and immune response activation, has recently emerged as an important player in cancer biology." (PMID 40868292, 2025). "The NOD2 gene has an allele mutation (3020insC) that signifies an increased risk of cancer, i.e., 25-35% higher than people without it." (PMID 38361685, 2024). "Recent investigations have pointed out that aberrant NOD2 expression is tied to cancer progression." (PMID 39353904, 2024). "Nevertheless, discrepancies exist regarding the effect of NOD2 on different types of cancer." (PMID 39353904, 2024). "Nonetheless, our findings provide an important basis for the prognosis and treatment of LUAD, and they indicate that Nod2 could be a potential therapeutic target for cancer." (PMID 37452162, 2023). "The correlation between NOD2 expression and tumorigenesis varies across different cancer types." (PMID 35130902, 2022). "Nucleotide-binding oligomerization domain 2 is also involved in cancer progression and chemotherapy resistance, which further suggests that P. micra regulation of NOD2 might induce CRC." (PMID 36517053, 2022). "NOD2 is a component of the innate immune system and represents a promising target for enhancing the innate immune response as well as the immune response against cancer cells." (PMID 36237313, 2022).